CYP3A4 (cytochrome P450 family 3 subfamily A member 4)
Diseases named in the same sentence as CYP3A4 in open-access papers (continued):
Sharing a sentence is not in itself a finding about the gene and the disease.
liver fibrosis (2 papers, 2018 to 2023). "An additional aim was to analyze the association between the degree of liver fibrosis, level of liver inflammation, and potential impact of applied antiviral and antiretroviral therapeutics on the expression of CYP3A4, CYP2B6, and ABCB1 transporters in this patient population." (PMID 37512019, 2023). "The mRNA levels of CYP2B6, CYP3A4, and ABCB1 was quantified and compared between the groups, along with the analysis of liver fibrosis and inflammation levels." (PMID 37512019, 2023). "Also, it has been reported that ASV were metabolized by CYP3A4 and P-glycoprotein, and that hepatic mRNA expressions of CYP3A4 and OATP1B1 decrease with the progression of liver fibrosis." (PMID 30308053, 2018). "Thus, the differences in the serum ASV concentrations depending on the severity of liver fibrosis should be evaluated in the future in reference to UGT1A1 SNPs and hepatic mRNA expressions of CYP3A4 and OATP1B1." (PMID 30308053, 2018).
medulloblastoma (2 papers, 2022 to 2025). A malignant, invasive embryonal neoplasm arising from the cerebellum. "HIF1α promoted drug resistance in human medulloblastoma by inhibition of CYP2B6, CYP3A4 and CYP3A5 expression, which in turn resulted in decreased conversion of CPA and IFA into their active forms and thus to diminished cytotoxicity." (PMID 35355718, 2022).
metastatic colorectal cancer (2 papers, 2008 to 2020). "A total of 132 metastatic colorectal cancer patients were genotyped for CYP3A4*1B, CYP3A4*18, CYP3A5*3, DPYD*2A, DPYD*5, DPYD c.1774C > T, UGT1A1*28, UGT1A1*6, ABCB1 c.1236C > T, ABCB1 c.3435C > T, ABCC2 c.3972C > T, and ABCG2 c.421C > A." (PMID 32778670, 2020).
morbid obesity (2 papers, 2015 to 2019). An excess of body weight, normally defined as an individual with a body mass index greater than 35 or a body weight greater than one hundred percent of ideal body weight. "The urinary excretion of M3OL was 27% lower in morbidly obese individuals compared to the normal-weight group (8.23 vs 5.97 nmol), providing additional evidence that CYP3A4 activity is lesser in morbid obesity." (PMID 31892725, 2019). "It is worth noting that both CYP3A4 and CYP2D6 activities are altered in morbid obesity although they follow different patterns (the first is decreased whereas the second is increased)." (PMID 31892725, 2019).
multiple myeloma (2 papers, 2015 to 2022). "Among anti-myeloma agents, dexamethasone is a strong inducer of CYP3A4 and P-glycoprotein and an inhibitor of P-glycoprotein; bortezomib is a CYP3A4 inhibitor; and venetoclax is an inhibitor of P-glycoprotein." (PMID 36551701, 2022).
myelofibrosis (2 papers, 2021 to 2026). A partial or complete replacement of the bone marrow stroma by fibrous tissue. "Ruxolitinib exposure is increased in GvHD patients in comparison to myelofibrosis patients due to reduced clearance and comedication with CYP3A4 or CYP2C9 inhibitors." (PMID 34505930, 2021).
post-traumatic stress disorder (2 papers, 2023 to 2024). An anxiety disorder precipitated by an experience of intense fear or horror while exposed to a traumatic (especially life-threatening) event. "Miscellaneous diseases and traits that were associated with CYP3A4 include cytokine levels, post-traumatic stress disorder (PTSD), heel bone mineral density, height, offspring birth weight, lymphocyte count, C-reactive protein levels, and triglyceride levels." (PMID 39457450, 2024).
Skin rash (2 papers, 2016 to 2024). A red eruption of the skin. "Moreover, the major metabolite of NVP produced by CYP3A4, 12-OH-NVP38, has been implicated in hepatotoxicity and skin rash caused by NVP15,39,40." (PMID 39604537, 2024). "Hence concomitant treatment with the CYP3A4 inhibitor ketoconazole, for example, increases the area under the curve (AUC) and could result in increased toxicities such as skin rash or diarrhoea." (PMID 26823680, 2016).
sleep disorder (2 papers, 2019 to 2020). A change from the patient's baseline sleeping pattern, in the hours slept and/or an alteration/dysfunction in the stages of sleep. "Sleep disorders and related medications, such as benzodiazepines, are commonly used in elderly, and these medications are mainly metabolized by CYP3A4 and induce side effects or attenuate therapeutic effects." (PMID 31736751, 2019).
soft tissue sarcoma (2 papers, 2014 to 2022). A malignant neoplasm arising from muscle tissue, adipose tissue, blood vessels, fibrous tissue, or other supportive tissues excluding the bones. "Higher expression of CYP3A4 and CYP3A5 than in adjacent normal tissues has been reported in studies on rhabdomyosarcoma, which is the most common soft tissue sarcoma in children." (PMID 36359206, 2022).
toxicity (2 papers, 2022 to 2023). The degree to which an agent can damage an organism. "As per our findings, a significantly higher number of individuals with CYP3A4 rs35599367 CT genotype developed renal toxicity which might be a result of the significantly elevated tacrolimus trough levels in these recipients." (PMID 36246675, 2022).
21-hydroxylase deficiency (1 paper, 2014). "Gomes and colleagues in 2009 implicated CYP2C19/CYP3A4 in 21-hydroxylation of progesterone in individuals with 21-hydroxylase deficiency thus affecting levels of mineralocorticoids." (PMID 24690327, 2014).
Addison’s disease (1 paper, 2024). "The European Medicines Agency (EMA) stated that contraindications for the use of finerenone are hypersensitivity to the drug, Addison’s disease and the simultaneous use of strong CYP3A4-inhibitors because finerenone is mainly cleared by CYP3A4." (PMID 39769473, 2024).
adrenocortical carcinomas (1 paper, 2025). "However, while active CYP3A4 has been identified in adrenocortical carcinomas, it is unclear whether adrenal medullary or PC12 cells express this isoform." (PMID 41020847, 2025).
alopecia (1 paper, 2019). Hair loss usually from the scalp. "On the other hand, patients with CYP3A4 rs2740574 A/G genotypes are more likely to develop alopecia (OR = 6.87, CI = 1.02–46.06, p-value = 0.047)." (PMID 30914949, 2019). "Univariate statistical analyses revealed that patients with ERCC2 rs13181 T/G and/or CYP3A4 rs2740574 A/G genotypes are more likely to develop alopecia; patients with ERCC2 rs238406 C/C genotype may develop leukopenia, and patients with GSTT1-null genotype could develop lymphocytopenia (III–IV)." (PMID 30914949, 2019).
asthenia (1 paper, 2023). Clinical sign or symptom manifested as debility, or lack or loss of strength and energy. "At allele level, the G allele for rs2242480 (CYP3A4, p = 0.02) and the C allele for rs776746 (CYP3A5, p = 0.022) were also associated with grade 1 of asthenia." (PMID 36982571, 2023).
atherosclerosis (1 paper, 2025). A disease characterized by the build-up of fatty material and calcium deposition in the arterial wall resulting in partial or complete occlusion of the arterial lumen. "CYP3A4 was involved in all metabolism pathways, and CYP2B6 was linked to lipid metabolism and atherosclerosis." (PMID 41155650, 2025).
Atrophy (1 paper, 2024). Any weakening or degeneration, especially through lack of use. "Thus, it can be concluded that CYP3A4 expression decreases due to intestinal atrophy caused by gluten ingestion and that, in cases of being treated with a GFD, the mucosa is restructured, and, therefore, CYP3A4 expression increases." (PMID 38790748, 2024).
autonomic neuropathy (1 paper, 2025). An inherited or acquired peripheral neuropathy affecting the autonomic nervous system. "Case reports and small series associate concurrent azoles (including posaconazole) with increased neurotoxicity, notably autonomic neuropathy and constipation, likely via CYP3A4 inhibition." (PMID 41295177, 2025).
autosomal dominant hypophosphatemic rickets (1 paper, 2021). Autosomal dominant hypophosphatemic rickets (ADHR) is a hereditary renal phosphate-wasting disorder characterized by hypophosphatemia, rickets and/or osteomalacia. "An autosomal dominant inheritance pattern causing disease in offspring of either gender should raise the possibility of autosomal dominant hypophosphatemic rickets (mutation in the FGF23 gene) or vitamin D–dependent rickets type III (mutation in the CYP3A4 gene)." (PMID 33660084, 2021).
bacterial pneumonia (1 paper, 2023). Acute infection of the lung parenchyma caused by bacteria (e.g., Streptococcus pneumoniae, Haemophilus influenzae, Chlamydia pneumoniae, Mycoplasma pneumoniae, and Legionella pneumophila). "In cases of bacterial pneumonia, the mRNA expression of MAPK1 and CYP3A4 increased significantly, while those of PTGS1 and PTGS2 decreased synonym." (PMID 37741847, 2023).
bone sarcoma (1 paper, 2025). A sarcoma that arises from the bone. "While the expression of certain CYPs, such as CYP3A4/5, has been investigated in bone sarcomas, the expression of CYP1B1 in bone sarcomas remains unclear." (PMID 41155673, 2025).
bowel dysfunction (1 paper, 2025). Any disease in which the causes of the disease is a perturbation of the lower digestive tract leading to its dysfunction. "Biomarker research investigating genetic polymorphisms in drug-metabolizing enzymes (CYP2D6, CYP3A4) and neurotransmitter receptors could identify patients at highest risk for developing medication-induced bowel dysfunction, enabling personalized medicine approaches." (PMID 41327232, 2025).
brain cancer (1 paper, 2021). A primary or metastatic malignant neoplasm affecting the brain. "Specifically, they are primarily metabolised by CYP3A4, which also metabolises several brain cancer chemotherapeutics including CPA and vincristine." (PMID 33477420, 2021).
brain tumors (1 paper, 2023). "Dexamethasone, for example, is commonly co-prescribed in patients with brain tumors receiving DOACs and AEs and could amplify the DOAC AE DDI because it also induces P-gp and CYP3A4." (PMID 37122531, 2023).
candidiasis (1 paper, 2020). Infection with the organism Candida. "Overall, (S)-8g had a pharmacological profile to pursue further biological investigations such as a murine candidiasis assay and cytochrome P450 inhibition assays (e.g. CYP3A4, CYP2D6)." (PMID 32784450, 2020).
cervical cancer (1 paper, 2019). A primary or metastatic malignant neoplasm involving the cervix. "In the research conducted by a team of Bangladeshi researchers, the impact of CYP3A4*1B polymorphism on cervical cancer susceptibility was tested." (PMID 31025537, 2019).
childhood cancer (1 paper, 2021). "In conclusion, adult female CCSs carrying the CYP3A4*3 allele appear to have a five-fold lower ovarian function after treatment for childhood cancer, and CYP2B6*2 may have a protective effect on AMH levels in patients receiving CED scores of 8000mg/m2 or more." (PMID 34572825, 2021).
cholangitis (1 paper, 2023). An acute or chronic inflammatory process affecting the biliary tract. "The constructed nomogram included seven parameters, namely recipient CYP3A4 genotype, pre-transplant cholangitis, GRWR, spleen long diameter, serum albumin, graft volume reduction, and donor CYP genotype." (PMID 37928356, 2023). "In multivariate logistic analysis, seven potential predictors were identified, including recipient CYP3A4 genotype, cholangitis before LT, GRWR, spleen long diameter, serum albumin, graft volume reduction, and donor CYP3A4 genotype." (PMID 37928356, 2023).
colonic adenoma (1 paper, 2005). "Western blot analyses of CYP2E1, CYP3A4, and CYP3A5 were performed with specimens obtained from 25 patients with colonic adenoma and 27 disease-free controls." (PMID 16281975, 2005). "However, in the present study protein levels of CYP2C8, CYP3A4, and CYP3A5 were found to be significantly lower in normal unaffected colonic mucosa of patients with colonic adenoma in comparison with disease-free controls." (PMID 16281975, 2005). "Therefore, the aim of the present study was to determine expression and protein concentrations of four representative CYPs (e.g. CYP2C, CYP2E1, CYP3A4, and CYP3A5) in macroscopically normal colonic tissue of subjects with and without colonic adenomas." (PMID 16281975, 2005).
contact dermatitis (1 paper, 2023). An inflammatory skin condition caused by direct contact between the skin and either an irritating substance or an allergen. "However, topical ketoconazole has its own disadvantages, including contact dermatitis, rashes, and medication interactions with the CYP3A4 enzymes if used over an extended period." (PMID 36600812, 2023).
Crohn disease (1 paper, 2022). A gastrointestinal disorder characterized by chronic inflammation involving all layers of the intestinal wall, noncaseating granulomas affecting the intestinal wall and regional lymph nodes, and transmural fibrosis. "In biopsy samples, investigators have demonstrated a decrease in CYP3A4 and PXR mRNA expression in inflamed small-intestinal tissue versus noninflamed duodenum within individual subjects (children) with Crohn’s disease but not in controls." (PMID 36359206, 2022).
Dravet syndrome (1 paper, 2019). "It would have been of interest to measure Css, min levels of stiripentol given that many children with Dravet syndrome would also be taking this medication and stiripentol is metabolized by CYP2C19 and CYP3A4 isoenzymes." (PMID 31333569, 2019).
Dystonia (1 paper, 2013). An abnormally increased muscular tone that causes fixed abnormal postures. "In this case, we report a glossopharyngeal dystonia secondary to a lurasidone-fluoxetine CYP-3A4 interaction to highlight the importance of maintaining an index of suspicion for laryngeal dystonia, a potentially fatal dystonia." (PMID 23762720, 2013).
edema (1 paper, 2019). An abnormal accumulation of fluid beneath the skin, or in one or more cavities of the body. "In vivo study showed that licorice increase the level of CYP3A4 and Nrf2, alleviate pulmonary edema, injury, and fibrosis, reduce the accumulation of PQ in vivo, protect or improve the liver and renal function of mice, and ultimately improve the survival rate of mice." (PMID 31182998, 2019).
enteropathy (1 paper, 2019). "In CYP3A4-humanized mice, a marked decrease in simvastatin metabolism was observed in response to enteropathy." (PMID 31234270, 2019). "As a preclinical test of this hypothesis, we measured the plasma concentrations of SV and its major metabolites in mice expressing the human CYP3A4 transgene in the small intestine, in whom acute enteropathy had been induced using polyinosinic-polycytidylic acid (poly I:C)." (PMID 31234270, 2019). "Therefore, the assessment of the functional activity of CYP3A4 may serve as a biomarker for enteropathy." (PMID 31234270, 2019).
Ewing sarcoma (1 paper, 2022). A small round cell tumor that lacks morphologic, immunohistochemical, and electron microscopic evidence of neuroectodermal differentiation. "The main clinical consequences of aberrant intratumoral expression of CYP3A4 may be mediated by administration of anticancer drugs that are CYP3A substrates during the treatment of Ewing’s sarcoma." (PMID 36359206, 2022). "It has been demonstrated that CYP3A4 overexpression may correlate with metastasis of Ewing’s sarcoma." (PMID 36359206, 2022).
gallstones (1 paper, 2016). Solid crystalline precipitates in the biliary tract, usually formed in the gallbladder, resulting in the condition of cholelithiasis. "In contrast, another study reported substantially reduced CYP3A4 expression in liver samples of patients with gallstone-related biliary obstruction." (PMID 28008998, 2016).
gastrointestinal stromal tumor (1 paper, 2023). "A physiologically based pharmacokinetic (PBPK) model for imatinib describing the CYP3A4-mediated autoinhibition during multiple dosing in gastrointestinal stromal tumor patients with normal renal function was previously reported." (PMID 37514108, 2023).
Headache (1 paper, 2025). Cephalgia, or pain sensed in various parts of the head, not confined to the area of distribution of any nerve. "Demographic factors may also contribute; women and younger adults tend to experience medication-related headaches more frequently due to hormonal and vascular factors, while racial differences in CYP3A4 and CYP3A5 metabolism may underlie variable adverse effect profiles." (PMID 41562805, 2025).
herpes zoster (1 paper, 2011). A common dermal and neurologic disorder caused by reactivation of the varicella-zoster virus that has remained dormant within dorsal root ganglia, often for decades, after the patient's initial exposure to the virus in the form of varicella (chickenpox). "Thus, we cannot rule out an excess risk of zoster in patients making concomitant use of ICS and potent inhibitors of CYP3A4 such as ritonavir." (PMID 22177425, 2011).
Hyperbilirubinemia (1 paper, 2023). An increased amount of bilirubin in the blood. "BIC is substrate for cytochrome P450-3A4 (CYP3A4) and uridine diphosphate glucuronosyltransferase 1 family, polypeptide A1 (UGT1A1), but the mechanism of hyperbilirubinemia, though looks similar to cabotegravir, remains to be defined." (PMID 36691090, 2023).
hyperthyroidism (1 paper, 2025). Overactivity of the thyroid gland resulting in overproduction of thyroid hormone and increased metabolic rate. "Hyperthyroidism has been shown to decrease the half-life of some drugs metabolized by CYP3A4, including digoxin, methimazole, and some beta-blockers; however, a study of 10 patients in an iatrogenic hyperthyroid state found that metabolism of midazolam decreased." (PMID 39901894, 2025).
Infertility (1 paper, 2021). "Identifying pharmacogenetic risk factors for alkylating agent-related gonadotoxicity such as the presence of a CYP3A4*3 allele may improve risk prediction models for reduced ovarian function and consequent infertility in female CCSs." (PMID 34572825, 2021).
intestinal cancer (1 paper, 2016). "Relative amounts of mRNA expression of CYP3A5 was much higher than those of CYP3A4 mRNA in HCT-8 human intestinal cancer cells that originates from ilocecum." (PMID 27119350, 2016). "By contrast to the impacts of OTA, AFB1 led to marginal changes of expression of CYP3A4 whereas it had partially suppressive effects on CYP3A5 mRNA expression in both intestinal cancer cells." (PMID 27119350, 2016). "However, OTA treatment increased CYP3A4 mRNA expression, but decreased CYP3A5 mRNA expression in both intestinal cancer cells." (PMID 27119350, 2016).
intracranial hemorrhage (1 paper, 2021). Bleeding within the SKULL, including hemorrhages in the brain and the three membranes of MENINGES. "Use of clopidogrel in patients with contraindication to ticagrelor (e.g. history of intracranial hemorrhage, moderate‐to‐severe hepatic impairment, concomitant use of strong CYP3A4 inhibitors) is reasonable." (PMID 33982795, 2021).
intrahepatic cholestasis (1 paper, 2022). A cholestasis characterized by impairment of the bile flow caused by obstruction located in the liver. "TZD is metabolized via CYP2C9 and CYP3A4 to a quinone metabolite, which induces oxidative stress and lead to intrahepatic cholestasis." (PMID 35372314, 2022).
lentivirus infection (1 paper, 2014). Virus diseases caused by the Lentivirus genus. "The increased activity of CYP3A4 was dose-dependent with regard to lentivirus infection and reached a plateau of an eight- to ten-fold increase with an MOI of 1,000." (PMID 24733486, 2014).